STAT3 (signal transducer and activator of transcription 3)
Diseases named in the same sentence as STAT3 in open-access papers (continued):
Sharing a sentence is not in itself a finding about the gene and the disease.
tumor (continued). "Secreted Hsp90 from PCa cell lines rapidly activates STAT3 in prostate fibroblast cell lines, leading to the activation of the pro-inflammatory NF-κβ pathway and secretion of inflammatory mediators known to augment PCa tumor survival and proliferation, such as IL-6 and IL-8." (PMID 24722453, 2014). "In addition, we found that metformin could inhibit IL-6 enhancement of tumor growth, as well as reduce tumor metastasis, through inhibition of STAT3-mediated EMT." (PMID 24789104, 2014). "Thus, STAT3 has emerged as a potential target for tumor immunotherapy." (PMID 25594054, 2014). "This marked inhibition of tumor growth by combination treatment could be because of H-4073-mediated inhibition of STAT3, Akt and FAK signaling pathways as well as reduction in the formation of new blood vessels by reducing VEGF production and inhibiting VEGF signaling." (PMID 24675768, 2014). "In addition, we examined whether activated STAT3 expression is increased in hypoxic regions of human tumor samples." (PMID 25594014, 2014). "However, the role of STAT3 for tumor formation appears complex." (PMID 24473086, 2014). "Several recent studies have shed insights into how STAT3 might mediate tumor suppressor effects." (PMID 24995504, 2014). "Thus, our working hypothesis was that IL-28 functions an intermediate protein in the signaling between MDSCs and tumor cells, which activates STAT3 in neoplastic cells and leads to cancer metastasis and angiogenesis." (PMID 25075523, 2014). "In addition, a human phase 0 study of a STAT3 decoy oligonucleotide suggested that it might yield effective therapeutic agent for reducing STAT3 target genes and inhibiting tumor growth." (PMID 24675568, 2014). "It is natural to ask whether activated STAT3 is a good or bad prognostic marker in a tumor." (PMID 24762632, 2014). "Hence, depending on the tumor, the relation between HspB1 and STAT3 may have different consequences." (PMID 24514166, 2014). "Thus, STAT3 knockdown prior to temozolomide therapy may reduce the incidence of tumor resistance to chemotherapy." (PMID 24518612, 2014). "Therefore, we hypothesized that targeting STAT3 could reverse the resistant phenotype in tumor cells, thereby enhancing the anti-tumor effects of cisplatin treatment in HNSCC." (PMID 24675768, 2014). "STAT1 is another protein shown to be regulated by STAT3 but may support or suppress tumor growth." (PMID 24743777, 2014). "Taken together, our study suggests that the combined targeted inhibition of STAT1, ARTD8, ARTD9 and/or DTX3L could increase the efficacy of chemotherapy or radiation treatment in prostate and other high-risk tumor types with an increased STAT1- and STAT3-signaling." (PMID 24886089, 2014). "Therefore, we next investigated the effects of CA and OA on STAT3 activation in tumor cells." (PMID 24738052, 2014). "Therefore, STAT3 appears to function as a tumor suppressor in the background of PTC." (PMID 24662939, 2014). "Thus, once again, the activation state of STAT3 reveals only part of the biology of a tumor." (PMID 24762632, 2014). "Moreover, the observations that STAT3 silencing suppressed tumor cell growth more effectively in an in vivo microenvironment than in in vitro cultures strongly suggest that the role of STAT3 in facilitating tumorigenesis is mainly attributed to its effects on the tumor cell-extrinsic signaling." (PMID 24662939, 2014). "Furthermore, recent evidences indicate that STAT3, apart from being a target for anti-cancer therapy, may also represent a crucial target for cancer prevention as STAT3 plays an essential role in tumor formation and initiation." (PMID 24380387, 2013). "To test whether inhibition of the JAK/STAT3 pathway would affect the growth of pediatric solid tumors, we evaluated the anti-tumor activity of AZD1480, an ATP competitive inhibitor of JAK1 and JAK2, which has been shown to decrease the growth of adult tumors in several pre-clinical models." (PMID 23531921, 2013).
tumor (continued). "Studies using an in vivo orthotopic mouse model showed that knocking down STAT3 (BxPC3/shSTAT3) delayed tumor progression and increased sensitivity to gemcitabine supporting the in vitro findings that STAT3 may be a relevant target for improving therapeutic responses." (PMID 24025152, 2013). "Thus, inhibiting STAT3 in high RON expressing cells may provide a novel approach for enhancing tumor response to gemcitabine." (PMID 24025152, 2013). "Finally, to confirm whether the strong and persistent Stat3 phosphorylation in MDSC-potentiated cancer cells is crucial to spontaneous tumor metastasis, we generated Stat3-knockdown 4T1 (4T1_shStat3) cells." (PMID 24021059, 2013). "Moreover, high levels of STAT3 in both malignant and normal tissues adjacent to the tumor have been detected, suggesting that STAT3 activation may occur before any detectable histological changes in the prostate." (PMID 23738079, 2013). "Moreover, much of the growth that stimulates the cross-talk between immune and IECs or malignant cells is mediated by cytokines that activate the oncogenic transcription factor STAT3, a major intrinsic activator in cancer inflammation and a regulator of the tumor microenvironment." (PMID 23379788, 2013). "Therefore, we sought to assess whether local inhibition of NF-κB within tumor cells only, global inhibition of STAT3 activity in all cells, or both were sufficient to reduce tumor growth in vivo." (PMID 24244348, 2013). "The functional interference of STAT3 homodimers using STAT3 transcription decoys or small molecules in structure-activity relationship (SAR) studies could successfully inhibit the growth of tumour cells." (PMID 23384097, 2013). "Targeting STAT3 may be an effective approach to addressing tumor progression." (PMID 23382965, 2013). "Moreover, previous studies have identified an immunomodulatory circuit initiated by STAT3 activation in tumor cells that drives anti-inflammatory cytokine production that, in turn, induces STAT3 activation within neighboring tumor infiltrating DC and converts them into regulatory cells." (PMID 24073274, 2013). "Thus, in addition to oncogenic roles, PcG proteins may function as tumor suppressors by inhibiting specific signaling pathways regulating cell growth, such as Stat3 signaling." (PMID 23192652, 2013). "Altogether, these data point to different tumor-associated factors (i.e., IL-10, IL-6, PGE2) exerting their suppressive effects at various stages of myeloid DC development through converging and communicating signaling elements encompassing the JAK2/STAT3 and p38-MAPK pathways." (PMID 24324467, 2013). "We therefore determined whether IL-6 mediated IL-17-driven Stat3 activation in a tumor setting." (PMID 24453427, 2013). "Since tumor-associated macrophages express higher concentrations of cytokines including IL-6, increased IL-6 may be one mechanism that leads to aberrant activation of JAK/STAT3 pathway in pediatric sarcomas." (PMID 23531921, 2013). "Although the adverse effects on normal immune cells should be avoided, targeting STAT3 or Wnt/β-catenin pathway by specific inhibitor in tumor cells and immunosuppressive cells, or along with other immunotherapy, might restore the immunocompetence of EC patients." (PMID 23819113, 2013). "We next tested whether the Stat3 inhibitor WP1066 shows antitumor activity against B16 tumor cells." (PMID 24453427, 2013). "Moreover, B cells around tumor vasculature exhibited persistently activated STAT3." (PMID 23734190, 2013). "In view of the important role of STAT3/EGFR signaling in tumor development and progression, the methods to inhibit EGFR in conjunction with oncogenic STATs may represent a novel and attractive therapeutic strategy for cancers characterized by upregulation of EGFR signaling." (PMID 23118721, 2012).
tumor (continued). "However, compared to surgery alone, M-HIFU combined with surgery were found to significantly inhibit the growth of rechallenged tumors, down-regulate intra-tumoral STAT3 activities, increase cytotoxic T cells in spleens and tumor draining lymph nodes (TDLNs), and improve the host survival." (PMID 22911830, 2012). "In our study, the lack of an association between p-STAT3 expression and CNS metastasis may be attributed to the fact that the systemic tumor biology may not be reflective of the tumor microenvironment immediately preceding development of CNS metastasis." (PMID 22488042, 2012). "Furthermore, STAT3 has been shown to be a key regulator of tumor-mediated immune suppression." (PMID 22488042, 2012). "Yet IL-17A could promote tumor growth in conjunction with IL-6-dependent activation of Stat3." (PMID 22855687, 2012). "Our mRNA and protein expression measurements weretherefore designed based on IFN-α signaling and did not include an IL-24 group.Our goal was to understand if combining IFN-α with IL-24 could enhanceanti-tumor activity via inhibition of STAT3 to promote anti-angiogenic effects." (PMID 22569271, 2012). "Whether targeted therapies aiming to the elimination of such tumour subpopulation or STAT3 inhibitors shown to induce differentiation of immature cell phenotype to a more radiosensitive cell population can improve the efficacy of radiotherapy is a hypothesis supported by the current findings." (PMID 22333601, 2012). "In addition to increasing tumor cell proliferation and survival, STAT3 also suppresses anti-tumor immunity which might explain why STAT3 was found to be more strongly activated in the C57BL/6 mice." (PMID 23251519, 2012). "Signal transducer and activator of transcription 3 (STAT3) is a transcription factor that is activated in response to growth factors and cytokines, and which contributes to the regulation of cell proliferation, apoptosis, and motility in many human tumour types." (PMID 21730976, 2011). "In the present study we further investigate whether monocyte expression of STAT3 in the tumor microenvironment could promote tumor growth and whether the STAT3 inhibitor, NSC 74859, can prevent diethylinitrosamine (DEN)-induced HCC by suppressing STAT3 activation and its associated inflammation." (PMID 22136659, 2011). "Moreover, we observed STAT3 activation in infiltrated monocytes adjacent to tumor tissue." (PMID 22136659, 2011). "Besides promoting tumor cell proliferation and inhibiting cell apoptosis, the activation of STAT3 in cancer cell has also shown to increase the capacity of tumor to evade the immune system, by inhibiting the maturation of dendritic cells and suppressing the immune response." (PMID 22136659, 2011). "STAT3 and pSTAT3 expressions were not determined to associate with tumor capsulation (P = 0.21)." (PMID 21575192, 2011). "However, recent studies have shown STAT3 to have both oncogenic and tumour suppressor function." (PMID 21338529, 2011). "In Ras-transformed cancer cells, serine phosphorylated Stat3 may also aid tumour growth by promoting metabolic functions in mitochondria possibly through its association with Grim19, and stimulation of the electron transport chain in a transcription independent way." (PMID 20478049, 2010). "Therefore, FLLL32 is not only potent in cancer cells in vitro but also in tumor cells in animal model in vivo and may have future potential to target tumor cells that express persistently activated STAT3 in cancer patients." (PMID 20712901, 2010). "Simultaneously, levels of the biologically active phospho-STAT3 were decreased and correlated with reduced transcription of the cell cycle regulating gene c-Myc and proliferation marking Ki-67, pointing to a potential mechanism by which Curcumin slows tumor growth." (PMID 20840775, 2010).
tumor (continued). "Moreover, Stat3 plays an important role in determining the outcome of the interaction between cancers and immune cells, both in terms of suppressing anti-tumour activities as well as facilitating a tumour promoting inflammatory microenvironment." (PMID 20478049, 2010). "Since blocking Stat3 function in tumor cells is also known to activate adaptive immunity it may be that IL-6 induced Stat3 is in part responsible for no/low activation of NK cells in the co-cultures of NK cells and either HEp2 cells or UCLA-1 or HOK-16B tumors." (PMID 20661281, 2010). "Therefore, Stat3 is an apt upstream target for inhibiting tumor VEGF expression and angiogenesis." (PMID 20204067, 2010). "Importantly, IL17 and IL23 alongside IL22 and cell-autonomous acting IL21, all promote and stabilize the Th17 phenotype and sustain inflammation through various Stat3-dependent feed-forward loops within the tumour, stromal and haematopoietic cells of the microenvironment." (PMID 20478049, 2010). "Interestingly, unlike spleen Treg cells, tumor-associated Treg cells express IL-23R and activates STAT3 in response to IL-23, leading to upregulation of the Treg-specific transcription factor Foxp3 and the immunosuppressive cytokine IL-10." (PMID 20885915, 2010). "It promotes tumor cell survival and proliferation in vitro through up-regulation of Stat3 and Bcl2 gene expressions, the cell cycle entry from G0/1 into S-phase, and the nuclear expression of NF-κB, which contribute to the tumorigenicity of tumor cells in vivo." (PMID 20975993, 2010). "The skewed anti-inflammatory gene response elicited by prolonged Stat3 activation in myeloid cells, on the other hand, curbs the immune system's anti-tumour response, while excessive Stat3 activation in inflammatory Th17 T-cells further fuels tumour growth and angiogenesis." (PMID 20478049, 2010). "Since Stat3 inhibition also blocks VEGF expression in tumours characterized by aberrant activation of Src, therapeutic targeting of Stat3 may inhibit neovascularisation in tumours associated with excessive signaling through epidermal growth factor receptor." (PMID 20478049, 2010). "Cytokines secreted by the activated tumor stroma modulate tumor growth and regulate their survival and invasiveness through activation of oncogenic signaling pathways in tumor cells, examples being activation of NF-κB by TNFα and IL-1β, and activation of STAT3 by IL-6." (PMID 20661477, 2010). "Furthermore, human tumor xenograft studies in mice have repeatedly demonstrated that inhibiting Stat3 results in decreased tumor growth and improved animal survival by inducing apoptosis in tumor cells, inhibiting angiogenesis and enhancing anti-tumor immune-mediated cytotoxicity." (PMID 19274102, 2009). "Pretreatment of monocytes with JSI-124, resulted in a significant reduction in STAT3 activity (measured by both STAT3 transcription factor assay or phospho-STAT3 intracellular immunostaining) and in IL-10 production by the monocytes in tumor cell:monocyte co-cultures." (PMID 19718269, 2009). "Given our results, one may speculate that at the pre-malignant stage physical interactions between resident APCs and tumor cells that activate STAT3 play a significant role in tumor escape, long before tumors are visible and large enough to secrete significant amounts of APCs-modulating factors." (PMID 19718269, 2009). "Consequently, compounds that target Stat3 while sparing Stat1, leaving its anti-oncogenic functions unopposed, may result in a synergistic anti-tumor effect." (PMID 19274102, 2009). "In addition, STAT3 activation through phosphorylation in tumor cells has been demonstrated to negatively regulate the adaptive immune responses both by reducing pro-inflammatory cytokine production, and by production of soluble factors inhibiting DC maturation." (PMID 19519895, 2009).
tumor (continued). "Based upon our previous insight into a contact-dependent effect of hMSC on APC phenotype and function, along with the linking of this effect to STAT3 activation, we now tested whether a similar contact-dependent STAT3 activation is also induced in tumor cell-APC interaction." (PMID 19718269, 2009). "Interestingly, levels of total STAT3 expression also varied among tumor samples." (PMID 19284568, 2009). "This activation occurs through the JAK/STAT3 signaling pathway, and mediates phenotypic changes in the treated cells, including enhanced cell proliferation and transformation of the cells to increase production of cytokines, which may promote tumor formation." (PMID 18939993, 2008). "Thus, STAT3 inhibition, even if suboptimal, would slow tumour progression." (PMID 16804520, 2006). "Upregulation of STAT3 levels in various cancers might even suggest this functions as an ‘oncogene’ or ‘tumour progression’ gene." (PMID 16804520, 2006). "In vivo validation confirmed icaritin suppressed tumor growth and M2 macrophage infiltration via the ALDOB/STX16/autophagy/STAT3 axis." (PMID 41731604, 2026). "STAT3 and HIF-1α cooperate to regulate gene expression under hypoxic conditions, enhancing tumor survival, angiogenesis, and metabolic adaptation." (PMID 41596231, 2026). "STAT3 can cooperate with HIF-1α to enhance carbonic anhydrase IX (CAIX) gene transcription, especially in hypoxic tumor microenvironments." (PMID 41596231, 2026). "IL6/IL6R/STAT3 and HIF1α/ZEB1 pathways induce epithelial to mesenchymal transition (EMT) and CAFs secrete EGF, FGF and HGF for tumour growth." (PMID 41476776, 2026). "This study provides new insight into the oncogenic role of tumour-resident fungi and highlights the M. restricta EV-JAK2/STAT3 axis as a potential therapeutic target for immune modulation." (PMID 42249590, 2026). "TRIM22 attenuates BC progression by targeting the JAK-STAT/STAT3 axis through CCS-mediated degradation, resulting in suppressed STAT3 phosphorylation and reduced tumor invasiveness." (PMID 41601694, 2026). "Upstream, tumor-stromal interactions may contribute to PDIA6 upregulation, as cancer-associated fibroblast-derived C-X-C motif chemokine ligand 12 (CXCL12) activated C-X-C chemokine receptor 4 (CXCR4)-dependent signal transducer and activator of transcription 3 (STAT3) signaling in vitro." (PMID 42234404, 2026). "Studies have shown that the signal transducer and activator of transcription 3 (STAT3) signaling is central in mediating astrocyte activation and subsequent tumor-promoting functions." (PMID 41560805, 2026). "H3K9la enhances the expression of interleukin-11 (IL-11), which subsequently triggers immune checkpoint activation through the JAK2/STAT3 signaling pathway, ultimately impairing CD8+ T cell activity and facilitating tumor growth." (PMID 41491598, 2026). "Specific inhibitors of IL-17RA signaling, such as the STAT3 inhibitor Stattic, reduced the expression of CD133, LGR5, ALDHA1, SOX2 and c-MYC, as well as tumor sphere formation in SW620 cells." (PMID 41438576, 2026). "In the tumor microenvironment across various cancer types, IL-6/JAK/STAT3 signaling promotes tumor cell growth, survival, invasiveness, and metastasis, while significantly suppressing the antitumor immune response." (PMID 41596531, 2026). "Within the tumor microenvironment (TME), exosome-derived ZFAS1 remodels intercellular communication networks, promoting angiogenesis via STAT3/VEGFA signaling, though its immunometabolic regulatory mechanisms warrant further elucidation." (PMID 41450817, 2026). "The pathways affected are: Ephrin Receptor Signaling, TGF-β Signaling, STAT3 Pathway, EGF Signaling, Tumor Microenvironment Pathway, BAG2 Signaling Pathway, H-17A Signaling Pathway, EIF2 Signaling." (PMID 41717271, 2026).